MIR615 (microRNA 615)
Synonyms: hsa-mir-615; MIRN615; mir-615
Gene: MicroRNA gene on chromosome 12 (54,033,950 to 54,034,045, forward strand). Ensembl gene ENSG00000207571.
Gene Ontology:
Biological process: miRNA-mediated post-transcriptional gene silencing
Cellular component: RISC complex